RNY1P15 (RNY1 pseudogene 15)
Gene: Miscellaneous RNA gene on chromosome 9 (122,945,988 to 122,946,094, reverse strand). Ensembl gene ENSG00000222351.
Homologues: Orthologues: chimpanzee Y_RNA (100% identical), macaque Y_RNA (92% identical). Paralogues in human: Y_RNA (89% identical), RNY1 (88% identical), Y_RNA (88% identical), RNY1P11 (87% identical), RNY1P10 (86% identical), Y_RNA (86% identical), Y_RNA (85% identical), Y_RNA (84% identical), RNY1P8 (83% identical), Y_RNA (83% identical), Y_RNA (82% identical), RNY1P5 (81% identical), and 97 more.